CX3CR1 (C-X3-C motif chemokine receptor 1)
Diseases named in the same sentence as CX3CR1 in open-access papers (continued):
Sharing a sentence is not in itself a finding about the gene and the disease.
atherosclerosis (continued). "However, inhibition of H2S formation by PAG increased aortic CX3CR1 and CX3CL1 expression and exacerbated the extent of atherosclerosis." (PMID 22815945, 2012). "Ly6C+ monocytes are recruited to mouse atherosclerosis via CCR2, CCR5 and CX3CR1." (PMID 21526997, 2011). "In summary, CX3CL1/CX3CR1 is involved in the progression of atherosclerosis and may be an effective therapeutic target, but no effective therapeutic agents have been developed." (PMID 40508161, 2025). "Cx3cr1creERT2/+ mice could not be used to assess the role of resident macrophages in atherosclerosis because Cx3cr1 heterozygosity affects the development of atherosclerosis." (PMID 39231480, 2024). "Therefore, we predict these mechanisms of T cell-induced endothelial damage are operative in atherosclerosis of HIV-uninfected persons and are accelerated in PLWH who live in a state of sustained chronic inflammation and have increased CX3CR1+ CD8 T cell numbers." (PMID 32976527, 2020). "CX3CL1 expression by dysfunctional endothelium and/or smooth muscle could provide a mechanism to attract and bind effector CX3CR1+ CD8 T cells and this may be important in the initiation and progression of atherosclerosis in both PLWH and in HIV-uninfected persons." (PMID 32976527, 2020). "CMV infection in PLWH is also associated with expansion of CD8+ T cells expressing fractalkine receptor (CX3CR1; involved in endothelial homing and adhesion) and the PAR-1 receptor which can be activated by thrombin, although the impact of these cells on clinical atherosclerosis is unknown." (PMID 31275317, 2019). "As the only member of the CX3C chemokine receptor subfamily, CX3CR1 binds to its sole endogenous ligand CX3CL1, which shows notable potential as a therapeutic target in atherosclerosis, cancer, and neuropathy." (PMID 35767622, 2022). "A subset of CD16-positive monocytes produces high levels of inflammatory mediators and up-regulates a number of chemokine receptors, including CCR2, CX3CR1 and CCR5 which are attributed non-redundant and independent roles in the development of atherosclerosis." (PMID 25875611, 2015). "Here we investigated the role of CD8 T cells in atherosclerosis in a non-human primate model of HIV infection and in the HIV-uninfected elderly; we sought to identify factors that promote the activation, function, and recruitment to endothelium of CX3CR1+ CD8 T cells." (PMID 32976527, 2020).
Alzheimer disease (58 papers, 2011 to 2025). A progressive, neurodegenerative disease characterized by loss of function and death of nerve cells in several areas of the brain leading to loss of cognitive function such as memory and language. "In expanding our research to the 3xTg model, we observed that CX3CR1+ Tregs significantly contribute to reducing hallmark features of Alzheimer’s disease, such as Aβ accumulation and microglial activation." (PMID 39769442, 2024). "In a mouse model of Alzheimer’s disease, CX3CR1 deficiency was reported to trigger microglia dysfunction, and exacerbate neurotoxicity and phosphorylation of tau, leading to neuronal synaptic dysregulation and the impairment of memory function." (PMID 37234914, 2023). "In particular, in mouse models of Alzheimer disease, CX3CR1 deficiency induces a reduction of Aβ proteins accumulation due to the increase phagocytic activity of microglia." (PMID 26347402, 2015). "Similar results with increased IL1β resulting from loss of Cx3cr1 were shown in two Alzheimer's disease mouse models and other CNS diseases." (PMID 25987130, 2015). "Accordingly, in several animal models of neuropathologies, including Parkinson disease, amyotrophic lateral sclerosis, stroke, and Alzheimer's disease, deficiency of fractalkine or of CX3CR1 leads to an increased production of proinflammatory molecules." (PMID 26347402, 2015). "Knocking out CX3CR1 reduced neuron loss and amyloid-beta deposition in Alzheimer's disease mouse models, and interfered with formation of thalamocortical synapses during development, when fractalkine is overexpressed." (PMID 25329999, 2014). "In Alzheimer’s disease (AD) and Parkinson’s disease (PD) animal models, CX3CR1 deficiency shows paradoxical outcomes, attenuating or exacerbating amyloid-β (Aβ) and tau pathologies in AD, while consistently worsening α-synuclein-induced neurodegeneration in PD." (PMID 41424797, 2025). "Cx3cr1, the receptor for the chemokine Cx3cl1 (fractalkine), has been implicated in the progression and severity of Alzheimer’s disease-like pathology in mice, but the underlying mechanisms remain unclear." (PMID 26038823, 2015). "In a triple transgenic (3xTg: PS1M146V knock-in, transgenic APPSwe and tauP301L) model of Alzheimer’s disease (AD) it was shown that loss of Cx3cr1 resulted in the increase of microglial migration and prevented neuronal loss while levels of Aβ deposition remained unaltered." (PMID 24655482, 2014). "In addition, a decrease in the number of amyloid plaques as well as a decrease in neuronal loss has been observed in CX3CR1-null mouse models of Alzheimer's disease." (PMID 22028924, 2011). "The analysis identifies VCAM1-mediated neuroinflammatory pathways in the superior parietal lobule and CX3CR1-regulated synaptic pruning in the putamen as key pathophysiological hubs in Alzheimer's disease." (PMID 41459562, 2025). "One of the first studies on the role of CX3CR1 in Alzheimer’s disease used CX3CR1-KO mice that were crossed with a triple-transgenic mouse model carrying presenilin, APP, and tau mutations." (PMID 39940727, 2025). "Nevertheless, later studies confirmed the neuroprotective effects of CX3CR1 suppression in different Alzheimer’s disease mouse models." (PMID 39940727, 2025). "Regarding other neuropsychiatric disorders, the CX3CL1/CX3CR1 axis was shown to contribute to the pathology of Alzheimer's disease (AD) by altering the levels of Tau protein and the process of Tau phagocytosis in microglia cells." (PMID 35782435, 2022). "Despite being rarely observed in healthy young adult mice, DM are widespread upon chronic stress, ageing, in CX3C chemokine receptor 1 (CX3CR1)-knockout (KO) mice, and in Alzheimer’s disease pathology (APP/PS1 model)." (PMID 33668314, 2021). "In fact, in a model of Alzheimer disease (AD), heterozygosity of Cx3cr1 in male mice resulted in reductions of pathology." (PMID 34130712, 2021).
Alzheimer disease (continued). "Microglial CX3CR1/CX3CL1 axis plays a significant role in the progression of Alzheimer’s disease with controversy in Aβ and Tau pathology." (PMID 32944223, 2020). "In this review, the pathophysiological roles of CX3CR1/fractalkine signalling in microglia and neurons at different stages of Alzheimer’s disease and the possible role of CX3CR1/Tau signalling has been widely discussed." (PMID 32944223, 2020). "The therapeutic potential of CX3CL1 in Alzheimer’s disease is more complex; however, knockout of CX3CR1 appears to be detrimental in mouse models of tauopathy, but beneficial in amyloid expressing mice." (PMID 32410624, 2020). "More interestingly, knocking out CX3CR1 in Alzheimer’s disease mice showed reduced Aβ deposition and increased microglial phagocytic activity." (PMID 32625064, 2020). "Full deletion of CX3CR1 in mouse models of Alzheimer's disease have opposing effects on amyloid-β and tau pathologies raising concerns about the benefits of targeting CX3CR1 for treatment of this disease." (PMID 31849963, 2019). "In Alzheimer's disease complete deletion of CX3CR1 in models of amyloid deposition reduced Aβ deposits and enhanced microglial Aβ phagocytic ability." (PMID 31849963, 2019). "Controlling neuroinflammation via CX3CR1 signaling was particularly beneficial in the pathogenesis of Alzheimer's disease." (PMID 30245686, 2018). "There was also reduced microglial expression of CX3CR1 and P2RY12 as they adopted a disease-associated phenotype in mouse models of Alzheimer’s disease and MS." (PMID 30087595, 2018). "Conversely, some studies showed a neurotoxic role for CX3CL1 in CX3CR1−/− mice models for Alzheimer's disease and stroke." (PMID 30245686, 2018). "While some studies with Alzheimer’s disease mouse models have suggested that CX3CR1 and CCR2 play a role in the progression of disease, we determined that having a single copy of either gene does not alter plaque deposition or microglial CD45 reactivity." (PMID 28923083, 2017). "Further support of this is demonstrated in the α-synuclein-induced inflammation model of Alzheimer’s disease, where the use of CX3CR1 knockout mice has been demonstrated to reduce inflammation during this disease state compared to wild-type mice." (PMID 27561705, 2016). "Many progressive neuroinflammatory disorders that are associated with increased microglial activation, such as Alzheimer's disease, show disruption of the FKN/CX3CR1 communication system." (PMID 24352739, 2013). "Alternatively, deletion of CX3CR1 leads to enhanced phagocytosis of amyloid beta plaques by microglia in Alzheimer’s disease, requiring the microglia to be present at the lesion sites." (PMID 23998480, 2013). "For example, neuron death was mitigated by Cx3cr1 deletion in models of Alzheimer's disease and ischemia." (PMID 22093090, 2011). "Alternatively, Cx3cr1 gene deletion has been shown to limit microglial-mediated neuron death in Alzheimer's disease." (PMID 22093090, 2011). "Alzheimer’s disease mouse model for investigation of microglial CX3CR1." (PMID 41424797, 2025). "Moreover, plasma-soluble CX3CR1 levels are significantly greater in people with mild to moderate Alzheimer’s disease than in people with severe disease." (PMID 39062768, 2024). "Despite its identification as a key checkpoint regulator of microglial activation in Alzheimer’s disease, the overarching role of CX3CR1 signaling in modulating mechanisms of Aβ driven neurodegeneration, including accumulation of hyperphosphorylated tau is not well understood." (PMID 35764973, 2022). "CX3CR1 signaling is known to regulate microglial phagocytosis in other contexts, such as synaptic phagocytosis during development, and amyloid plaque clearance in Alzheimer's disease models." (PMID 27314452, 2016).
Alzheimer disease (continued). "In models of lateral amyotrophic sclerosis, Parkinson’s disease (PS) and Alzheimer’s disease, the absence of CX3CR1 has been associated with a worse outcome possibly due to the chronic pro-inflammatory function of CX3CR1-deficient microglia." (PMID 25904895, 2015). "A disruption in fractalkine-CX3CR1 signaling by opiate-HIV protein exposure would parallel evidence from a variety of other CNS disorders where fractalkine-CX3CR1 interfacing appears to be altered, including Parkinson's and Alzheimer's diseases, as well as in HIV dementia." (PMID 22093090, 2011). "CX3CR1 deficiency results in microglia activation and increased neurodegeneration after LPS injections in PD and amyotrophic lateral sclerosis (ALS) mouse models and worsens Alzheimer’s disease (AD)-related neuronal deficits associated with microglial activation and elevated chemokines." (PMID 41373544, 2025). "Similarly, CX3CR1 polymorphisms that decrease receptor activity or affinity for FKN are linked to enhanced disease progression in amyotrophic lateral sclerosis, Alzheimer’s disease and neuroinflammatory pathologies." (PMID 32625064, 2020). "Thus, neuronal Cx3cr1 may impact Alzheimer’s disease-like pathology by modulating conformational state-dependent amyloid-β-induced synaptotoxicity." (PMID 26038823, 2015). "The chemokine receptors CCR2, CCR5, CXCR2, CXCR3, CXCR4 and CX3CR1 are constitutively expressed in the human brain, and their expression is enhanced under pathological conditions, including stroke and neurodegenerative diseases like HIV-associated dementia (HAD) and Alzheimer’s disease (AD)." (PMID 23210607, 2012). "Also, a recent article showed that lowering CX3CR1 levels or partially inhibiting its activity in the brain might be a therapeutic strategy to increase neuronal Aβ clearance, reduce Aβ levels and delay progression of Alzheimer’s disease." (PMID 32625064, 2020). "We hypothesize that CX3CR1/Tau signalling could be involved in the synthesis of pro-inflammatory cytokines, enhanced microglial activation and migration that ultimately leads to neuro-inflammation and neuronal damage in neurodegenerative diseases such as Alzheimer’s disease." (PMID 32944223, 2020). "In models of Alzheimer’s disease (AD), multiple sclerosis (MS) and neurotoxin models of PD, the chemokine CX3CL1 (fractalkine) and its receptor (CX3CR1) have important roles in modulating neuroinflammation." (PMID 26469270, 2015). "In Alzheimer’s disease (AD), CX3CL1/CX3CR1 blockade modulates microglia phagocytic activity in a way that markedly attenuates amyloid deposition." (PMID 25152714, 2014). "On the other hand, the complete depletion of CX3CR1 has been demonstrated to worsen Parkinson’s disease, amyotrophic lateral sclerosis, experimental autoimmune encephalomyelitis (EAE) and Alzheimer’s disease." (PMID 23998480, 2013). "It is well known that in the pathology of Alzheimer’s disease, there is a condition of generalized and progressive inflammation during its evolution, both occurring in the brain system, then endothelial cells expressing CX3CL1 and its receptor CX3CR1." (PMID 38473758, 2024). "Contrariwise, the CX3CL1 membrane form in Alzheimer’s disease has a negative effect on preventing tau phagocytosis by its competition in binding the microglia receptor CX3CR1." (PMID 37175729, 2023). "In models of Alzheimer disease produced by overexpression of APP/PS1 or human APP, CX3CR1 knockout results in decreased levels of pro-inflammatory cytokines Tumor Necrosis Factor (TNF) and monocyte chemotactic protein 1 (CCL2) but increased Interleukin 1-beta (IL1β)." (PMID 26469270, 2015). "Additionally, the lacking of CX3CR1 was cytotoxic in models of amyotrophic lateral sclerosis, Parkinson’s disease, and Alzheimer’s disease." (PMID 32664984, 2020).
Alzheimer disease (continued). "Therefore, the apparent harmful effects of CX3CR1 activation occurring in situations resembling Alzheimer’s disease may not be attributable exclusively to microglial activity, and instead they could be due to a combination of the actions of different cells present in the brain." (PMID 39940727, 2025). "For instance, whilst the activation of FKN and/or CX3CR1 signalling may provide novel opportunities for the treatment of Alzheimer's Disease (AD), this does not represent a strategy for neuropathic pain where a blockade of FKN and/or CX3CR1 would be desirable." (PMID 35295489, 2021).
colitis (53 papers, 2011 to 2026). Inflammation of the colon. "Loss of HDAC3 in CX3CR1 positive monocytes or macrophages attenuated the activation of inflammasomes and tissue damage in mouse colitis." (PMID 38903915, 2024). "In this model, CX3CR1+ macrophages serve as a cellular source of IL-23, akin to the scenario observed in the IL-10-deficient colitis model." (PMID 39379604, 2024). "In contrast, CX3CR1 deficiency in mice resulted in a higher susceptibility to DSS colitis that was exacerbated upon C. albicans challenge." (PMID 37998910, 2023). "In the intestine, mice deficient in either CX3CR1 or CX3CL1 exhibited severe colitis in comparison to littermate controls, due to the decreased number of IMφs and enhanced commensal bacteria translocation." (PMID 35593111, 2022). "Consistent with the observation that CX3CR1+ MNPs-depleted mice exhibit gut microbiota alteration and severe DSS-induced colitis, the CX3CR1 gene missense mutation in CD patients is associated with impaired antifungal antibody responses." (PMID 35619716, 2022). "Tregs prevent ILC3-associated colitis by inhibiting IL-23 and IL-1β production from intestinal-resident C-X3-C Motif Chemokine Receptor 1 (CX3CR1)+ macrophages, which restrains ILC3-linked IL-22 production." (PMID 34299236, 2021). "Altogether, these results indicate that the loss of CD98hc in CX3CR1+ macrophages attenuated dextran sodium sulfate-induced colitis in mice." (PMID 32188932, 2020). "Cx3cr1 is involved in the development and progression of chronic inflammatory diseases, such as colitis and arthritis while Cx3cr1 deficiency reduces the severity of these diseases." (PMID 32400390, 2020). "One study showed that loss of CX3CR1 or its ligand CX3CL1 rendered mice less susceptible to experimentally induced colitis." (PMID 32987848, 2020). "CX3CR1 deficiency in mice results in a decrease of lamina propria macrophages and increased severity of experimental colitis." (PMID 26932821, 2016). "Recently, it has been reported that deletion of IL-10Rα expression in CX3CR1+ cells renders mice susceptible to spontaneous colitis in a Helicobacter positive facility." (PMID 27027442, 2016). "A key suppressor of macrophage-associated inflammation is the IL-10/IL-10 receptor (IL-10R) axis, as mice bearing mutations in IL10-Ra in intestinal CX3CR1+ macrophages developed severe colitis comparable to the pathology reported for IL-10-deficient animals." (PMID 26082775, 2015). "Thus, CX3CR1+ macrophages are very important for pathogenic microbe elimination, and also experiments on mice showed that CX3CR1 deficient mice suffer from severe colitis." (PMID 37994325, 2023). "Increased CX3CL1/CX3CR1 in human and mouse models suggested that it could be a potential biomarker for colitis, and V249I polymorphism of the CX3CR1 gene is associated with intestinal strictures, particularly in smokers in CD patients." (PMID 37994325, 2023). "To examine whether a similar block was present during H. hepaticus-induced colitis, we used Cx3cr1+/gfp reporter mice, in which one allele of the Cx3cr1 gene has been replaced with the gene encoding green fluorescent protein (GFP)." (PMID 29203542, 2018). "Next, the CX3CL1–CX3CR1 axis has been shown to be required for optimal production of IL-10 by intestinal mφ 56 and finally, CX3CR1-deficiency has been reported to lead to decreased numbers of intestinal mφ 107,108 as well as altering susceptibility to chemically induced colitis." (PMID 24942685, 2014). "Within the subepithelial dome, populated by mononuclear phagocytes (MNPs) including dendritic cells and macrophages, we observed a marked increase in CD11c+ CX3CR1+ macrophages during colitis compared to healthy mice." (PMID 40546113, 2025). "To clarify the mechanism of HDAC3 in CX3CR1-positive monocytes in DSS-induced colitis, we then performed RNA sequencing to analyze the gene expression profiles in the colonic mucosa." (PMID 38903915, 2024).